IL1B (interleukin 1 beta)
Diseases named in the same sentence as IL1B in open-access papers (continued):
Sharing a sentence is not in itself a finding about the gene and the disease.
Insulin resistance (continued). "TNF-α, IL-6, IL-1β, and HOMA-IR were significantly lower in the semaglutide-treated group, suggesting that semaglutide has a beneficial effect on muscle function by reducing the inflammatory response and insulin resistance." (PMID 39125786, 2024). "Similarly, insulin resistance can induce activation of microglia in the hippocampus of young rats, alongside increased expression of inflammatory molecules COX-2 and IL-1β." (PMID 39456952, 2024). "IL-1β decreases IRS-1 tyrosine phosphorylation and its gene expression, inhibiting the insulin signaling pathway required for glycemic control and contributing to the development of insulin resistance." (PMID 37372020, 2023). "Moreover, increased glucose levels also contribute to a low-chronic inflammatory state and insulin resistance partly through NLRP3 inflammasome activation and IL-1β production in subcutaneous adipose tissue (SAT)." (PMID 37819510, 2023). "Circadian rhythm dysfunction promotes the secretion of inflammatory cytokines (TNFα, IL-1β, and IL-6), which induces insulin resistance and makes a negative effect on the production of GnRH and LH." (PMID 37229470, 2023). "Thus, the increased secretion of TNF, IL1B, and CCL2 in the hepatic macrophages of old mice potentially aggravates insulin resistance, liver steatosis, and the progression of chronic liver diseases." (PMID 37602516, 2023). "CRP is stimulated by IL-1β, TNF-α and IL-6 in the liver, which act together to activate serine and threonine kinases to suppress insulin signal transduction and thus promote insulin resistance." (PMID 37891561, 2023). "We found that JAZF‐1 and PPAR‐γ could promote Tregs differentiation and regulate insulin resistance by synergistically decreasing the expression levels of TNF‐α, IL‐1β and IL‐6 and increasing those of IL‐10 and TGF‐β." (PMID 36734198, 2023). "Brain insulin resistance occurs through the release of pro-inflammatory cytokines; peripherally produced pro-inflammatory cytokines such as TNF-α, IL-6, IL-12 and IL-1β can cross the blood-brain barrier, leading to neuroinflammation and central insulin resistance." (PMID 37415663, 2023). "Moreover, it has been demonstrated that High Fat diet induces insulin resistance through NLRP3 inflammasome activation, and by a subsequent IL-1β secretion and ROS production in mouse AT." (PMID 37819510, 2023). "Likewise, upstream of IL‐1β, the NLRP3 inflammasome pathway in myeloid cells also plays a part as a modulator of glucose metabolism and insulin resistance." (PMID 35971650, 2022). "It was found that endogenously synthesized n-3 PUFA blocked HF diet-induced NLRP3 inflammasome activation and the release of IL-1β in adipose tissue, stromal vascular fraction (SVF) and adipose tissue preadipocytes, which attenuated insulin resistance in HF diet-fed fat-1 mice." (PMID 36234919, 2022). "Grape powder extract (rich in quercetin-3-glucoside, catechin, epicatechin, rutin, gallic acid and resveratrol) showed to decrease LPS-stimulated inflammation in macrophages by affecting the gene expression of IL-6, IL-8, IL-1β and TNF-α, and in turn decreased insulin resistance." (PMID 35057523, 2022). "Moreover, punicic acid (5, 10, and 30 μM) significantly attenuated the levels of IL‐6, IL‐1β, and IFN‐γ following the TNF‐α‐induced insulin resistance in three T3‐L1 adipocyte cells." (PMID 36541264, 2022). "The cytokines can induce insulin resistance in β-cells and peripheral tissues and could activate the NLRP3 inflammasome leading to secretion of IL-1β." (PMID 35475576, 2022). "Macrophages participate in inflammatory pathways including JNK, IKK/NF-κB, and JAK/STAT through secreting inflammatory factors, such as TNF-α, IL-6, IL-1β, and LTB4, thereby inducing chronic inflammation of adipose tissue, liver, and muscle, further leading to insulin resistance." (PMID 36230963, 2022).
Insulin resistance (continued). "Dietary supplementation of resveratrol during late pregnancy showed a positive effect on the placental function of sows, with ameliorated insulin resistance (HOMA-IR), increased triglyceride (TG) levels, and reduced levels of inflammatory cytokines, such as IL-1β and IL-6." (PMID 36407549, 2022). "Moreover, TNF-α, IL-6, IL-1β, IFN-γ are also related to insulin resistance in the pediatric population." (PMID 36146688, 2022). "Moreover, IL-1β in GDM was related with glucose metabolism and insulin resistance, and IL-10 inversely correlated with neonatal birth weight." (PMID 35303833, 2022). "Kupffer cells play a major role in liver insulin resistance induced by HFD feeding through producing various inflammatory mediators, including TNF-α, IL-6, IL-1β, prostaglandins, and reactive oxygen species, which play vital roles in promoting the development of insulin resistance." (PMID 36230963, 2022). "The activation of the NLRP3 inflammasome could enhance the expression of IL-1β, IL-18, and interferonγ (IFNγ), while it inhibits IRS-1/PI3K/AKT signaling, thereby leading to insulin resistance." (PMID 36187801, 2022). "Visfatin, an adipokine present mainly in visceral adipose tissue, which induces the production of IL-6, IL-1β, and TNF-α, has a crucial inflammatory impact on the liver and maybe also related to insulin resistance." (PMID 35052633, 2022). "However, most previous studies estimated that IL-1β secreted from macrophages mediates macrophage-adipocyte cross-talk and impairs insulin signaling in human primary adipocytes, which might overlook the effect of pro-inflammatory cytokines released from preadipocytes on insulin resistance." (PMID 36234919, 2022). "The inflammatory cytokines, such as interleukin-1β (IL-1β) which is primarily driven by NF-κB and/or NLRP3 inflammasome activation, were related to islet inflammation and insulin secretion as well as the development of insulin resistance." (PMID 35111067, 2021). "Moreover, macrophage and Kupffer cell infiltration contribute to the progression of NAFLD and insulin resistance secreting pro-inflammatory cytokines such as TNF-α, IL-6 and IL-1β." (PMID 34684533, 2021). "Furthermore, IL-1β and MCP-1 produced by TNF-α-stimulated mouse adipocytes/monocytes were shown to induce insulin resistance in the liver and adipose tissues." (PMID 33859296, 2021). "These macrophages secrete TNF-α, IL-6, IL-1b and MCP1, which induce insulin resistance." (PMID 34683361, 2021). "After 12 months of TRE, body mass was reduced by 3.4% and inflammatory markers (IL-6, IL-1β, and TNF-α), lipid profile (HDL, LDL, TG), and insulin resistance (fasting glucose, insulin, HOMA-IR) significantly improved compared with ND without affecting muscle performance." (PMID 34649266, 2021). "In mice fed a high-fat diet (HFD), the lack of IL-1β was protective in terms of adipose tissue inflammation and insulin resistance." (PMID 33546399, 2021). "TNF induced insulin resistance in adipocytes by inhibiting insulin-induced IRS1 tyrosine phosphorylation and insulin-induced glucose uptake and played a role in angiogenesis by inducing VEGF production synergistically with IL-1B and IL-6." (PMID 34306139, 2021). "It is well-known that the overproduction of proinflammatory cytokines TNFα, IL-1β, IL-6, and MCP-1 might play a critical role in the development of insulin resistance and chronic inflammation in obese animals." (PMID 33297496, 2020). "The M1 macrophage may promote the development of insulin resistance through secretion of proinflammatory cytokine such as TNF-α, IL-6, and IL-1b in response to stimulation by INF-γ." (PMID 32971975, 2020). "We conclude, that IL-1β, presumably derived from the uterus and the placenta, contribute to the impaired glucose tolerance during GDM, possibly via changes in steroid-hormones and subsequent insulin resistance." (PMID 32080229, 2020).
Insulin resistance (continued). "Ultimately, we note that individuals with lipodystrophy have an increase in serum interleukins, keys of the inflammatory process, as IL-1β, TNF-α and IL-6 (p < 0.05 all), compared with healthy individuals, which can be the trigger to insulin resistance in this population." (PMID 29449893, 2018). "Preadipocytes release IL-1β, which both controls adipocyte differentiation and promotes adipocyte insulin resistance even in the absence of macrophages." (PMID 30116482, 2018). "IL-1β is a ligand for the IL-1 receptor which, like TLR4, signals via MyD88, IL-1 receptor-activated kinases (IRAK1 to 4), IKK, and NF-κB and should thus potentiate the whole model for insulin resistance in insulin target cells." (PMID 30116482, 2018). "In addition, these mice display increased inflammation in skeletal muscle as demonstrated by higher levels of IL-1β, caspase-1 and NLRP3, probably explaining the increased insulin resistance in these mice." (PMID 26405763, 2015). "Active caspase-1 can eventually process IL-1β and IL-18 precursors, serving as enhancer of multiple proinflammatory pathways including NF-κB, mitogen-activated protein kinase (MAPK), IFNγ, chemokines, and ROS and also promoting insulin resistance." (PMID 24744784, 2014). "Together, the data in both human and mouse show that MAP3K8 is involved in local adipose tissue inflammation, specifically for IL-1β and its responsive cytokines IL-6 and IL-8, but does not seem to have systemic effects on insulin resistance." (PMID 24586913, 2014). "Moreover, hsCRP and IL-1β and TNF-α and IL-6 positively correlated with insulin resistance (P < 0.05)." (PMID 24795503, 2014). "Interestingly, the inflammatory cytokines IL-1β, TNF-a, and IL-6 expression increased significantly and induced insulin resistance in the HFD-Nrf2-null group, compared with the HFD-WT group." (PMID 24188280, 2013). "IL1-β and TNFα induce IRS-2 phosphorylation, which leads to insulin resistance, followed by the apoptotic death of β cells; the inhibition of cytokines by AS101 may contribute to β cell preservation." (PMID 22761194, 2012). "Of note, elevated levels of TNFα, IL-1β, IL-6 and IL-10 mRNA in MO with high insulin resistance degree were not statistically different from the levels found in T2D-MO." (PMID 23110196, 2012). "In myeloid-specific Iκκ-β (an activator of NF-κB)-deficient mice, a decrease in proinflammatory cytokine production (IL-1β, IL-6, TNF-α, and MCP-1) and the inhibition of NF-κB activation has been reported, avoiding, in this way, the development of insulin resistance." (PMID 23326021, 2012). "Therefore, the activation of these signaling pathways induces the production of more IL-1β, TNF-α, and MCP-1 and high levels of iNOS expression, contributing to insulin resistance in different tissues." (PMID 23326021, 2012). "Moreover, in cultured cells, tissues and whole animals, NF-κB has been shown to activate TNFα, IL6, IL-1β, and plasminogen activator inhibitor 1 (PAI-1) inducing insulin resistance." (PMID 20508722, 2010). "This not only drives the sustained release of pro-inflammatory cytokines (such as IL-1β and TNF-α) but also disrupts insulin signaling through JNK/IRS-1 phosphorylation pathways, forming the pathological basis for chronic low-grade inflammation and insulin resistance." (PMID 40980312, 2025). "Mechanistically, increased TSH levels in subclinical hypothyroidism promoted the secretion of cytokines IL-1α, IL-1β and IL-6 by inducing macrophage M1 polarization, which upregulated EGR1 to transcriptionally activate LCN2 and SOCS3 in insulin target cells, thereby exacerbating insulin resistance." (PMID 40523992, 2025). "In addition, the independent effect of IL-1β on quality of life (per PDQ-39 scores) supports the hypothesis that inflammation exacerbates symptoms through oxidative stress and insulin resistance." (PMID 40672460, 2025).
Insulin resistance (continued). "An inflamed visceral fat pad produces pro-inflammatory adipokines including interleukin-1β (IL-1β), interleukin-6 (IL-6), and tumor necrosis factor-α (TNF-α), which contribute to the progression of systemic insulin resistance, type 2 diabetes, MAFLD, heart failure, and atherosclerosis." (PMID 39160276, 2024). "In a murine model of insulin-resistance induced by HFD feeding, the stimulation of bone marrow macrophages with omega-3 FAs suppressed the activation of the NLRP3 inflammasome, thereby inhibiting IL-1β secretion and resulting in improved metabolic alterations in vivo." (PMID 39083430, 2024). "Also, it has been shown the relative gene expression of pro-inflammatory cytokines such as IL1-β, IL-6, and TNF-α, and apoptosis reduced in insulin resistance-induced HepG2 models after treatment with a combination of metformin and MSC-EXO compared to other groups." (PMID 37153436, 2023). "Probiotics reduce insulin resistance and oxidative stress by increasing SOD (superoxide dismutase), GSH (glutathione), and catalase (CAT) activity, and reduce the expression of inflammatory cytokine tissue necrosis factor (TNF)-α, interleukin (IL)-1β, and IL-6." (PMID 37374359, 2023). "We assessed the gene expression of proinflammatory cytokines, such as IL-1β, IL-6 and TNF-α, as well as mTOR and IKKβ in the adipose tissues of the control and experimental rats in order to assess the ability of C. papaya to mitigate HFD-streptozotocin-incited inflammation and insulin resistance." (PMID 36826001, 2023). "TNF-α and IL-1β are pro-inflammatory cytokines and are known to have negative effects on the action of insulin, such as impairing glucose uptake by inhibiting the phosphatidylinositol-3-kinase (PI3K) and protein kinase B (Akt) pathway and promoting the de-elopement of insulin resistance." (PMID 36145139, 2022). "In addition to MAPKs, IL‐1β was shown to enhance the SOCS‐mediated degradation of IRS‐1/2 involving the IkappaB kinase beta (IKKβ)/NF‐κB pathway, promoting glucose intolerance and hepatic insulin resistance by this mechanism." (PMID 36101976, 2022). "Previous studies revealed that the production of lipid metabolites (diacylglycerol), proinflammatory cytokines (TNF-a, IL-1b, IL-6, monocyte chemoattractant protein-1) and cellular stress, including oxidative and endoplasmic reticulum stress, may contribute to FFA-induced insulin resistance." (PMID 35711703, 2022). "In this study, a HF diet activated NLRP3 inflammasome via inducing reactive oxygen species (ROS) generation and promoted IL-1β production primarily from adipose tissue preadipocytes, but not from adipocytes and induced insulin resistance in wild type (WT) mice." (PMID 36234919, 2022). "Pro-inflammatory cytokines such as IL-1β via oxidative stress induction, reduction of insulin signaling and glucose transport as well as elevation of FFA and up-regulation of hepatic NF-kβ have a central role in acute hepatitis, insulin resistance, glycemia, and dyslipidemia." (PMID 33995940, 2021). "In particular, we observe altered expression of genes previously reported to aggravate insulin resistance in both cell types, with the most profound changes seen for Cebpa (fold change 0.0096) and Lep (fold change 4.2) in 3T3-L1, ELOVL6 (fold change 8.88) and IL1B (fold change 3.92) in SGBS." (PMID 32718202, 2020). "Moreover, IL-1β, but not IL-18, is necessary to induce insulin resistance in adipose tissue treated with atorvastatin." (PMID 31652822, 2019). "Furthermore, NF-κB activation increases the transcription of IL-1β, IL-6, and TNF-α and hyperexpression of these mediators may contribute to insulin resistance." (PMID 29760586, 2018). "The cytokines TNF-α and IL-1β can phosphorylate insulin receptor substrate-1 to induce insulin resistance, while the Islet amyloid polypeptide deposited in the pancreas can activate the NLRP3 (Nod-like receptor family, Pyrin domain containing 3) inflammasome to drive IL-1β secretion." (PMID 25802557, 2015).
Insulin resistance (continued). "More importantly, whether IL-1β is responsible for macrophage-induced insulin resistance in human and rodent adipocytes has not been reported." (PMID 24918199, 2014). "We can speculate that in a condition of insulin-resistance (IR), several extracellular and intracellular stimuli, i.e., free fatty acids (FFA), ionic flux, extracellular ATP (eATP) and ROS may be increased and activate NLRP3 inflammasome and the release of IL-1β." (PMID 40526637, 2025). "Exercise intervention may inhibit the overactivation of NLRP3 inflammasome, leads to a decreased level of inflammatory cytokine IL-1β, which further fails to induce hepatic insulin resistance, thus enhancing insulin sensitivity and improving insulin resistance." (PMID 36817440, 2023). "Correlations between microbial taxa abundance and cytokine production (e.g., IL-1β, TNFA) in insulin-sensitive subjects, and the lack of these associations in insulin-resistant participants, suggest that insulin resistance may affect interactions between gut microbiome and host cytokines’ release." (PMID 35010920, 2021). "Therefore, the decreased number of hepatic macrophages and their M2-dominant polarization account, at least in part, for the attenuation of insulin resistance and steatohepatitis in febuxostat-treated CL diet-fed mice, even though the mRNA expression of Nlrp3 or Il-1β in the liver is not decreased." (PMID 31965018, 2020). "Inflammatory mediators, such as pro-inflammatory cytokines (TNF-α, IL-1β, and IL-8) as well as anti-inflammatory cytokines (IL-10 and TGF-β), can induce insulin resistance without affecting lipid breakdown." (PMID 40231066, 2025). "TNFα induces mitochondrial dysfunction, oxidative stress, and insulin resistance, which activate the adipose NLRP3 inflammasome without altering IL-1β." (PMID 37876013, 2023). "However, a recent study found that insulin resistance and liver histopathology in metabolically unhealthy subjects did not correlate with the hepatic abundance of NLRP3 inflammasome nor circulating IL-1β levels." (PMID 36817440, 2023). "Moreover, with the lack of NLRP3 and IL-1β, our findings revealed the improved insulin signaling cascade in vitro, suggesting the NLRP3 inflammasome as an important determiner of insulin resistance." (PMID 29096724, 2017). "Interestingly, in our study lack of IL-1RI in primary hepatocyte did not prevent insulin resistance induce by adipose tissue explants from WT-HFF mice, whereas the absence of IL-1β in the adipose tissue fragments did suggest involvement of IL-1β in adipose-hepatocyte crosstalk." (PMID 23341960, 2013).